ENSG00000252236
Synonyms: LOC124900449
Gene: Small nucleolar RNA gene on chromosome 1 (156,192,063 to 156,192,203, reverse strand). Ensembl gene ENSG00000252236.
Gene Ontology:
Biological process: RNA processing
Cellular component: nucleolus
Homologues: Paralogues in human: SNORA26 (55% identical).